ZNF143 (zinc finger protein 143)
Description:
Transcription factor that activates expression of genes transcribed by both RNA polymerases II and III, and which is required to safeguard mitochondrial activity. Specifically recognizes and binds the Staf-binding site (SBS), a consensus DNA-binding motif present in thousands of promoters. Activates the gene for selenocysteine tRNA (tRNAsec). Activates expression of small nuclear RNA (snRNA) transcribed by RNA polymerases II and III. Also activates expression of mRNAs and acts as a key regulator of cell proliferation and differentiation by specifically activating expression of a subset of nuclear-encoded mitochondrial genes, thereby controlling mitochondrial function (By similarity). Involved in the maintenance of embryonic stem cells by promoting association of POU5F1/OCT4 to promoters, leading to NANOG expresion (By similarity).
Synonyms: SBF; STAF; pHZ-1
Tractability: PROTAC: UniProt records ubiquitination sites on it; ubiquitination databases record sites on it; its protein half-life has been measured.
Gene: Protein-coding gene on chromosome 11 (9,460,319 to 9,529,002, forward strand). Ensembl gene ENSG00000166478.
Subcellular location: Nucleus; Chromosome
Subcellular location (Human Protein Atlas): Nucleoplasm; Golgi apparatus; Nuclear bodies; Vesicles
Pathways (Reactome):
Gene expression (Transcription): RNA Polymerase III Abortive And Retractive Initiation; RNA Polymerase III Transcription Initiation From Type 3 Promoter; RNA polymerase II transcribes snRNA genes
Gene Ontology:
Molecular function: chromatin loop anchoring activity; core promoter sequence-specific DNA binding; DNA-binding transcription activator activity, RNA polymerase II-specific; protein binding; RNA polymerase II cis-regulatory region sequence-specific DNA binding; DNA-binding transcription factor activity, RNA polymerase II-specific; transcription regulator activator activity
Biological process: chromatin looping; positive regulation of transcription by RNA polymerase II; regulation of DNA-templated transcription; regulation of transcription by RNA polymerase II; regulation of transcription by RNA polymerase III
Cellular component: nucleoplasm; chromosome; nucleus; chromatin
Genetic constraint (gnomAD): Loss-of-function variants: 42 observed, 67.48 expected, observed/expected ratio (o/e) 0.62, 90% interval 0.49 to 0.81. The upper end of that interval is the gene's LOEUF score, 0.81, which puts it in group 3 of 6, group 1 being the genes least tolerant of losing a copy. Missense variants: 610 observed, 800.37 expected, observed/expected ratio (o/e) 0.76, 90% interval 0.71 to 0.81. Synonymous variants: 299 observed, 292.17 expected, observed/expected ratio (o/e) 1.02, 90% interval 0.93 to 1.13.
Gene-disease validity (ClinGen):
ClinGen rates the evidence that ZNF143 causes each of these diseases.
methylmalonic aciduria and homocystinuria (autosomal recessive): Limited. An inborn error of vitamin B12 (cobalamin) metabolism characterized by megaloblastic anemia, lethargy, failure to thrive, developmental delay, intellectual deficit and seizures.
Homologues: Orthologues: chimpanzee ZNF143 (99% identical), macaque ZNF143 (99% identical), dog ZNF143 (99% identical), guinea pig ZNF143 (99% identical), rabbit ZNF143 (99% identical), pig ZNF143 (98% identical), mouse Zfp143 (97% identical), rat Zfp143 (97% identical), tropical clawed frog znf143 (74% identical), zebrafish znf143b (72% identical), zebrafish znf143a (62% identical). Paralogues in human: ZNF76 (52% identical), MTF1 (18% identical), PATZ1 (15% identical), ZNF148 (15% identical), ZNF384 (15% identical), ZNF362 (15% identical), PRDM10 (14% identical), ZBTB16 (14% identical), ZNF281 (14% identical), MAZ (13% identical), ZNF410 (13% identical), PRDM1 (13% identical), and 24 more.
Diseases named in the same sentence as ZNF143 in open-access papers:
ZNF143 is named in the same sentence as 36 diseases in open-access papers, as found by Europe PMC text mining. Sharing a sentence is not in itself a finding about the gene and the disease. The quoted sentences say what the papers report.
breast cancer (9 papers, 2012 to 2022). A primary or metastatic malignant neoplasm involving the breast. "The cell cycle, cancer, ErbB, HIF1a, NF-kB, Foxo, JAK–STAT, Wnt, and Notch pathways are among the main pathways connected to ZNF143 or its interactors, and these pathways are well-known to be potentially associated with breast cancer." (PMID 36675976, 2022). "Taken together, our results suggested that reduced ZNF143 played a role as a regulator for breast cancer malignancy and that autophagy is deeply associated with cancer survival." (PMID 30935019, 2019). "We draw the conclusion from this study that the transcription factor ZNF143 may be essential since it seems that ZNF143 regulates a broader variety of biological processes and pathways linked to breast cancer." (PMID 36675976, 2022). "Short-hairpin (sh) RNA-lentiviral particles against ZNF143 were used to infect benign breast cancer cells in order to knock down ZNF143 and learn more about the molecular mechanism underlying how it influences breast cancer progression (MCF7 sh-ZNF143)." (PMID 36675976, 2022). "ZNF143 expression in healthy tissues and tissues from different stages of metastatic breast cancer was examined using immunohistochemistry." (PMID 36675976, 2022). "An improved understanding of ZNF143 in the context of human breast cancer as well as enhancers in breast cancer and normal breast cell lines results from the integrated approach." (PMID 36675976, 2022). "Breast cancer cells with ZNF143 knockdown exhibited greater cellular motility in migration and invasion experiments." (PMID 36675976, 2022). "In this study, we have used an integrated approach to explore the relevance of ZNF143 in human breast cancer and have analysed the gene expression patterns and enhancers in human breast cancer; furthermore, we have also analysed their respective functions." (PMID 36675976, 2022). "The recurrent C→T conversion at the ZNF143 locus influences the chromatin loop formation and alters distal gene expression in breast cancer." (PMID 32318100, 2020). "ZNF143 knockdown induces increased breast cancer motility, which indicates that ZNF143 expression contributes to breast cancer progression." (PMID 32318100, 2020). "In detail, we showed the effects of ZNF143 on tumor malignancy from motility to dormancy in breast cancer cells by showing better survival of breast cancer cells under nutrient-deprivation when ZNF143 expression had been downregulated." (PMID 30935019, 2019). "Here, we first investigated if MCF7 breast cancer cells showed a difference in cell survival when cells were stressed, depending on ZNF143 expression." (PMID 30935019, 2019). "Importantly, a prior study discovered that breast cancer cells with low levels of ZNF143 expression outlived control cells (MCF7 sh-Control) under starvation when the autophagy-inhibiting drug chloroquine was present." (PMID 36675976, 2022). "Furthermore, we have displayed the co-expressed genes for ZNF143 as well as the pathways directly connected to ZNF143 in cases of breast cancer." (PMID 36675976, 2022). "We have concentrated on ZNF143 and its effect on human breast cancer in the discussion section." (PMID 36675976, 2022). "ZNF143 has been found in numerous cancers, such as lung adenocarcinoma, leukemia, colon cancer cells, prostate cancer, gastric cancer, and breast cancers, implying a role in tumor development." (PMID 30935019, 2019).
breast cancer (continued). "To determine if ZNF143 expression contributes to tumor malignancy, such as recurrence and metastasis in breast cancer patients, we compared disease-free survival between selected patients with altered ZNF143 expression and the remaining patients in the whole data set." (PMID 30935019, 2019). "The data from this study strongly support a role for ZNF143 during breast cancer malignancy." (PMID 30935019, 2019). "Notably, more foci were observed in sh-ZNF143 cells than in sh-Control cells, similar to the TEM data, implying a relationship between ZNF143 and the autophagic process in breast cancer cells." (PMID 30935019, 2019). "Almost 5000 proteins were profiled, and 177 proteins were selected based on altered ZNF143 expression (more than 1.2-fold or less than 0.83-fold in sh-ZNF143 cells compared to that in sh-Control controls, with a significant p-value), and were used for pathway analysis in breast cancer cells." (PMID 30935019, 2019). "ZNF143 knockdown has also been shown to increase cell motility in colon cancer cells and breast cancer cells; however, it remains unclear whether ZNF143 expression affects tumor malignancy by regulating cell biology more than motility, such as cell viability." (PMID 30935019, 2019). "Endogenous ZNF143 mRNA levels can even reach a 10-fold increased expression like in breast cancer." (PMID 24234445, 2014). "Thus, it may suggest that ZNF143 could be one of the most significant genes that may control the breast cancer-related signaling pathways." (PMID 36675976, 2022). "Thus, Notch1 and Znf143 may co-regulate Nanog expression in mammary tumor-initiating cells." (PMID 22992387, 2012). "While being known oncogenes, PAX9 and ZNF143 have not been extensively studied in breast cancer and none of these TFs have previously been implicated in the response to lapatinib." (PMID 22709873, 2012). "Importantly, we found that breast cancer cells with low expression levels of a zinc-finger protein, ZNF143 (MCF7 sh-ZNF143), showed better survival than control cells (MCF7 sh-Control) under starvation, which was compromised with chloroquine, an autophagy inhibitor." (PMID 30935019, 2019). "In stage IV breast cancer, for example, ZNF143 is 10 times more expressed than in normal tissue." (PMID 24234445, 2014).
gastric cancer (8 papers, 2019 to 2023). A primary or metastatic malignant neoplasm involving the stomach. "For instance, high expression of ZNF143 has been correlated with lymph node metastasis in gastric cancer, indicating that ZNF143 plays an important role in gastric cancer metastasis." (PMID 35164660, 2022). "It was previously reported that ZNF143 enhanced metastasis of gastric cancer cells by promoting the process of epithelial to mesenchymal transition through the PI3K/Akt signalling pathway." (PMID 35109781, 2022). "Multiple lines of evidence has unveiled that ZNF143 regulates the progression of many tumors including gastric cancer, ovarian cancer, colon cancer, and hepatocellular carcinoma." (PMID 35068350, 2022). "ZNF143 was also observed to enhance metastasis of gastric cancer by promoting the process of epithelial to mesenchymal transition through the PI3K/AKT signalling pathway." (PMID 35109781, 2022). "ZNF143 is one of the zinc finger proteins, which enhanced gastric cancer cell migration by promoting the process of EMT through PI3K/AKt signaling pathway." (PMID 33028966, 2020). "Previous studies have demonstrated that ZNF143 plays carcinogenic roles in diverse tumors, such as lung adenocarcinoma, gastric cancer and colon cancer." (PMID 31186064, 2019). "This study was aimed at identifying the role of zinc finger protein 143 (ZNF143) in gastric cancer (GC) progression." (PMID 32076462, 2020).
colon cancer (7 papers, 2019 to 2022). "ZNF143 is also involved in the migration and invasion of colon cancer cells through a ZEB1-E- cadherin-linked pathway." (PMID 32318100, 2020). "Loss of ZNF143 may contribute to the development of colon cancer by regulating intracellular and intercellular signalling for cell plasticity and the tumour microenvironment respectively." (PMID 30933430, 2019). "The expression levels of ZNF143 and IL-8 are inversely correlated with three-dimensionally grown spheroids and colon cancer tissues." (PMID 32318100, 2020). "The expression levels of ZNF143 and IL‐8 were inversely correlated with three‐dimensionally grown spheroids and colon cancer tissues." (PMID 30933430, 2019). "Among cytokines, IL‐8 attracted attention, with its significantly increased levels, as a secreted soluble factor in ZNF143‐knockdown colon cancer cells." (PMID 30933430, 2019). "THP‐1 cells were differentiated when cells were incubated with condition media from colon cancer cell with less ZNF143, drastically." (PMID 30933430, 2019). "Our data suggest a ZNF143‐dependent signalling mechanism that can modulate the autocrine activity of pro‐inflammatory cytokines to promote colon cancer progression." (PMID 30933430, 2019). "We observed that secretion of interleukin (IL)‐8 was increased when ZNF143 expression was reduced in two colon cancer cell lines." (PMID 30933430, 2019). "We examined the effect of ZNF143 knockdown on the cytokine profile of the colon cancer cell line HCT116." (PMID 30933430, 2019). "Stattic disrupted the activation of STAT3 in a time‐ and dose‐dependent manner, resulting in decreased IL‐8 expression, suggesting a role of STAT3 for IL‐8 expression in colon cancer cell with less ZNF143." (PMID 30933430, 2019). "Several studies have shown that expression of zinc‐finger protein 143 (ZNF143) is closely related to tumour progression including colon cancer." (PMID 30933430, 2019). "Additionally, earlier research has indicated that ZNF143 influences the motility of colon cancer cells." (PMID 36675976, 2022). "Here, we investigated whether ZNF143 expression affects the tumour microenvironment and tumour progression by screening molecules secreted by colon cancer cells stably expressing short‐hairpin RNAs against ZNF143 or control RNAs." (PMID 30933430, 2019). "Nuclear expression of ZNF143 was reduced as tumour malignancy increased in colon cancer tissue." (PMID 30933430, 2019). "Also, IL‐8 showed to be expressed more in colon cancer cells with less ZNF143, similar to data from monolayer culture." (PMID 30933430, 2019). "We further investigated whether ZNF143 knockdown had an effect on IL‐8 expression in colon cancer cells." (PMID 30933430, 2019). "Hence, this is the first study focused on ZNF143 and the regulation of IL‐8, which may be important for maintaining the tumour microenvironment and facilitating metastasis in colon cancer cells." (PMID 30933430, 2019). "Finally, we identified a negative correlation between ZNF143 and IL‐8 in the tissues of colon cancer patients, suggesting it may be of diagnostic importance." (PMID 30933430, 2019). "SB225002, an antagonist of CXCR2, reduced Tyr705 phosphorylation of STAT3 and IL‐8 protein expression in HCT116 colon cancer cells, which was also apparent in HCT116 sh‐ZNF143 cells." (PMID 30933430, 2019). "Furthermore, the expression of the human ZNF143 gene by transfecting a plasmid‐encoding full‐length human ZNF143 (pFLAG‐CMV‐hZNF143FL) reversed these effects according to RT‐PCR, implying that the transcription of IL‐8 may be regulated by ZNF143 in colon cancer cells." (PMID 30933430, 2019).
hepatocellular carcinoma (6 papers, 2021 to 2024). A malignant tumor that arises from hepatocytes. "Zinc finger protein 143 (ZNF143) is a transcriptional activator that mediates hepatocellular cancer cell cycle transition and cell proliferation." (PMID 38105608, 2024). "It has been reported that ZNF143-mediated H3K9 trimethylation upregulated CDC6 in hepatocellular carcinoma." (PMID 35109781, 2022). "CDC6, cell division cycle 6, whose expression was promoted by zinc finger protein 143 (ZNF143) and accelerated hepatocellular carcinoma cell-cycle progression." (PMID 34566519, 2021). "From these results, we can speculate that ZNF143 OE in normal liver cells can inhibit cell proliferation, whereas its high expression in hepatoma cells can promote cell proliferation." (PMID 35780101, 2022). "This high expression suggests that ZNF143 promotes the formation of hepatoma cells." (PMID 35780101, 2022).